MMP9 (matrix metallopeptidase 9)
Diseases named in the same sentence as MMP9 in open-access papers (continued):
Sharing a sentence is not in itself a finding about the gene and the disease.
liver fibrosis (184 papers, 2005 to 2025). "The bioinformatics analysis indicated that TNF, IL-6, PPARG and MMP9 were promising candidate genes that can serve as diagnostic and prognostic biomarkers for liver fibrosis." (PMID 39869574, 2025). "Gene expression of Col1a1, TGFβ-1, TIMP-1, MMP-2, and MMP-9, which are associated with liver fibrosis, was significantly higher in MCDHFD mice than in control animals." (PMID 37107346, 2023). "Several studies have shown that MMP2 and MMP9 are associated with liver fibrosis and that trans-THSG impeded fibrosis-associated extracellular matrix remodeling by inhibiting the transcription of MMP2 and MMP9." (PMID 35845925, 2022). "MMP2, MMP8, and MMP9 have all been reported to be associated with the progression of liver fibrosis and cirrhosis." (PMID 33315911, 2020). "In agreement, pro-fibrogenic factors implicated in liver fibrosis, such as TGFβ, COL1α1, matrix metalloproteinase-9 (MMP9), and interferon-α (IFNα), are consistently decreased after using MLN4924." (PMID 33195347, 2020). "In the hepatic fibrosis model infected by Schistosoma mansoni, the severity of fibrosis was most closely associated with the increased MMP-9 activity." (PMID 15642145, 2005). "Our results suggest that the progression of liver fibrosis in E. granulosus infection could be associated with upregulated expression of MMP9." (PMID 37235398, 2023). "Serum MMP-9 was negatively associated with the severity of liver fibrosis in chronic HCV patients." (PMID 36551935, 2022). "Furthermore, MMP9 is tightly associated with liver fibrosis as it can cleave different types of collagen besides other basal membrane proteins." (PMID 33777102, 2021). "MMP9 is a multifunctional protein, including mediating leukocyte traffic in hepatic ischemia and reperfusion injury, aggravating drug associated acute liver injury, regulating hepatic regeneration and liver fibrosis." (PMID 27907201, 2016). "The aim of this work was to develop a novel competitive enzyme-linked immunosorbent assay (ELISA) for measuring MMP-2 and MMP-9 mediated turnover of type VI collagen and to measure the neo-epitopes in two complementary experimental models of liver fibrosis induced by BDL or CCl4." (PMID 21935455, 2011). "Furthermore, we found the same outcomes in LX2 cells, indicating that CA-induced inhibition of hepatic fibrosis might be associated with the down-regulation of MMP9, TGF-β1, and the TGF-β1 receptor." (PMID 29403377, 2017). "Chlorogenic acid inhibits the expression of miR-21, α-SMA, and TGF-β, while increasing the protein expression of Smad7 and matrix metalloproteinase-9 (MMP-9), thereby alleviating liver fibrosis." (PMID 41154556, 2025). "Our findings suggest that TNF, IL-6, PPARG, and MMP9 are potential therapeutic targets that influence liver fibrosis progression by regulating inflammatory responses and apoptosis through multiple pathways." (PMID 39869574, 2025). "Studies have found that in mice with liver fibrosis treated with melatonin, MMP-9 activity is reduced and Nrf2 expression is increased." (PMID 39735699, 2024). "MMP-9 has also been shown to promote or inhibit liver fibrosis and wound repair, depending on the context." (PMID 38352492, 2024). "It is known that the activation of MMP-9 degrades collagen in liver, and for that reason, it is sometimes augmented in hepatic fibrosis, probably as a compensatory mechanism." (PMID 38539902, 2024). "The expression of selected liver fibrosis markers (both gene expression and MMP-9 levels) in LX-2 cells exposed to varying concentrations of crude MO extract and 1-PHE was evaluated using qRT-PCR and ELISA." (PMID 39201682, 2024). "Ly-6Clo subgroup macrophages primarily repair liver fibrosis by upregulating MMPs (MMP9, MMP12, and MMP13), which facilitates the degradation of ECM." (PMID 39635524, 2024).
liver fibrosis (continued). "In contrast, the same increase in ECM stiffness can lead to reduced MMP-9 activity in liver fibrosis, serving as a regulatory mechanism to limit ECM degradation and maintain fibrotic tissue structure." (PMID 38693104, 2024). "The activation of the TGF-β/SMAD signaling pathway in HSCs resulted in the upregulation of several key genes associated with hepatic fibrosis, including TIMP1, SMAD2, SMAD3, COL1A1, and MMP2, as well as increased secretion of MMP-9 protein." (PMID 39201682, 2024). "Analogously, MMP9 expression was attenuated in the later stages of the liver fibrosis model presented in this study, confirming hepatocyte impairment in ECM component degradation following aging." (PMID 38132319, 2023). "The SeP extracted from soybean alleviated liver fibrosis caused by chemokine ligands 4 (CCL4) by promoting GPxs synthesis and increasing the mRNA expression of matrix metallopeptidase 9 (MMP9) in rats." (PMID 38202719, 2023). "Targeting cIAPs, including BIRC3, has been suggested as a potential therapeutic strategy for liver fibrosis by increasing MMP9 expression induced by CCL5 chemotactic neutrophils." (PMID 38274787, 2023). "It was also found that the progression of liver fibrosis to HCC decreased with increased expression of MMP-9." (PMID 36978885, 2023). "It is worth noting that gelatinases such as MMP-9 are also considered potential targets for the treatment of liver fibrosis and hepatic repair as they scavenge TIMP-1 and are responsible for collagen degradation." (PMID 36978885, 2023). "HSC activation-induced MMP9 production plays an important role in hepatic fibrosis through LCN2/STAT3-mediated signaling." (PMID 37960230, 2023). "Liver fibrosis is caused by damage to its connective tissue, i.e., an increase in the amount of fibrous extracellular matrix, with MMP-2 and MMP-9 being particularly important in this process." (PMID 36769216, 2023). "Matrix metalloproteinases (MMPs), particularly MMP-2 and MMP-9, are upregulated in activated HSCs, which are pivotal to cell migration and responsible for liver fibrosis." (PMID 37034499, 2023). "Hepatoprotective effects (alleviated liver fibrosis caused by CCL4 by promoting GPxs synthesis and increasing MMP9 mRNA expression)." (PMID 38202719, 2023). "In chronic hepatitis B, a significantly higher expression of MMP-9 was observed with an increase in the degree of liver fibrosis." (PMID 35625637, 2022). "Along with this, the mRNA levels of several liver fibrosis-related genes (Col1a1, Mmp9, Timp1) were also increased in livers from Gm4951−/− mice." (PMID 35842425, 2022). "FFAs also activate M2 polarization in KCs to release TGF-β, in turn transforming HSCs to produce α-SMA, collagen type 1, and MMP9, leading to extracellular matrix accumulation and liver fibrosis." (PMID 36077452, 2022). "The levels of FN, collagen-I, collagen-III, collagen-IV, MMP-2 and MMP-9, which have been recognized to be as markers for liver fibrosis, were also analyzed by Western blot assay in HG-challenged HSC-T6 cells following captopril treatment." (PMID 34607529, 2021). "Our results exhibited that crude extract and its carotenoid enrich fractions play a dual role in liver fibrosis as preserved the balance between MMP9/TIMP1 ameliorating liver fibrosis." (PMID 33628797, 2021). "In the family of MMPs, MMP2 and MMP9 are particularly important for the development of liver fibrosis since they degrade type IV collagen (basal membrane)." (PMID 34301291, 2021). "We also studied FN, collagen-I, collagen-III, collagen-IV, MMP-2 and MMP-9 levels, which are markers for liver fibrosis." (PMID 34607529, 2021). "In comparison to NASH control: hAEC-CM:- Increased MMP-9 expressionAll treatments:- Reduced liver fibrosis area.- Reduced pSMAD 2/3 signaling (TGF-β1 signaling pathway)- Reduced activated hepatic stellate cells and liver macrophages." (PMID 35083233, 2021).
liver fibrosis (continued). "There were some literatures about MMP2 and MMP9 related to liver fibrosis, such as MMP9 was up-expressed in HCV patients with different stages of fibrosis, the activity of MMP2 and MMP9 in patients with liver cirrhosis were increased and so on." (PMID 34301291, 2021). "This current study is the first to explore the effects of crude extract and its carotenoid enrich fractions on liver fibrosis induced by TAA via increasing MMP9 and decreasing its inhibitor TIMP1expression." (PMID 33628797, 2021). "To address more specifically the role of MMP‐9 in liver fibrosis and portal hypertension, we performed MMP‐9 KO mice experiments." (PMID 34647412, 2021). "Blockade of iNOS by genetic deletion or by a specific inhibitor induced antifibrotic effects in a murine model of NASH that were accompanied by a decrease in MMP-9, suggesting an association among iNOS, MMP-9, and hepatic fibrosis." (PMID 33333846, 2020). "Hamsters that fed on HFD showed high levels of MMP2 and MMP9 in the liver, increase in these MMPs in liver generally correlates with liver fibrosis." (PMID 31653214, 2019). "On the transcriptomics level, the significant changes of gene expression of Mmp9, Tgfβ, observed after the first dose, indicate the response shift to liver fibrosis." (PMID 30956639, 2019). "Luteolin administration is known to reduce liver fibrosis associated MMP-2 and MMP-9 induced by Pentylentetrazol toxicity." (PMID 31170991, 2019). "The expressions of MMP-2 (known as gelatinase-A) and MMP-9 (known as gelatinase-B) are significantly upregulated in liver fibrosis for ECM remodeling." (PMID 31847284, 2019). "The ratio of matrix metalloproteinase-2 (MMP2) and its inhibitor TIMP2 has been found to be imbalanced in hepatic fibrosis whereas MMP-9/TIMP-1 ratio is dysregulated in liver metastasis." (PMID 30087389, 2018). "The state of liver fibrosis is supported by the increased Mmp9 expression levels in E. cloacae-treated mice." (PMID 29847581, 2018). "The results of our experiments showed that quercetin reduced BDL or CCl4 liver fibrosis, inhibited extracellular matrix formation, and regulated matrix metallopeptidase (MMP)-9 and tissue inhibitor of metalloproteinase (TIMP)-1." (PMID 28839277, 2017). "We found that CA provides protection against BDL-induced liver fibrosis by inhibiting MMP9 as well as TGF-β1 and its receptor, TGF-β R1." (PMID 29403377, 2017). "Macrophages contribute to ECM remodeling during both the injury and recovery phase of CCl4-induced liver fibrosis and are an abundant source of MMP-9 and MMP-13." (PMID 27672655, 2016). "Alternately, treatment with IL-10 has been demonstrated to significantly increase the production of MMPs, including MMP-9, as well as significantly decrease TIMPs during liver fibrosis." (PMID 27681697, 2016). "On the other hand, in thioacetamide-induced liver fibrosis, liver fibrosis was enhanced and the tissue repair delayed in decorin KO mice, and MMP-9 activity was lower in decorin KO mice." (PMID 27547834, 2016). "In this study, CCl4-intoxicated rats revealed significantly higher levels and expression of MMP-9 which is consistent with the previous studies conducted on chronic models of CCl4-induced liver fibrosis." (PMID 27776513, 2016). "High circulating TIMP-1 levels, furthermore, strongly promote liver fibrosis, implicating gelatinase B/MMP-9 in normal liver physiology, adding to its physiological roles in the nervous system, inflammation and immunology." (PMID 24473089, 2014). "In a mouse model of liver fibrosis, the BM-derived cells express matrix metalloproteinase (MMP)-13 and MMP-9 and contribute to the regression of liver fibrosis." (PMID 25551560, 2014). "It is interesting that the downregulation of MMP‐9 is entirely posttranslational, as so many genes relevant to liver fibrosis pathogenesis are regulated translationally." (PMID 25413315, 2014). "We showed that the proteolytic inactive MMP-9 E402Q mutant inhibits CCl4-induced liver fibrosis in rats." (PMID 25380300, 2014).
liver fibrosis (continued). "CCL2 has been shown to modulate MMP‐9, which is a factor that is relevant to liver fibrosis resolution." (PMID 25413315, 2014). "Future translational studies should test the effectiveness of human MMP-9 mutants in the resolution of liver fibrosis." (PMID 25380300, 2014). "Overexpression of MMP-9 in the mouse liver, using an adenovirus vector, reduces liver fibrosis after CCl4 treatment." (PMID 23755201, 2013). "Reduced liver fibrosis in CCL3−/− mice was associated with altered expression of Col1a1, TIMP1, and MMP9 (P<0.05)." (PMID 23799074, 2013). "We demonstrated that PPARα agonist significantly repressed hepatic expression of visfatin, and consequently reduced PI3K, MMP-2 and MMP-9 expression, thus suppressing the progression of ethanol mediated liver fibrosis." (PMID 23388073, 2013). "Liver from hAEC treated mice demonstrated significantly greater expression of MMP-9, which effectively degrades collagen, and significantly less MMP-12, which has been reported to inhibit the production of MMP-9 and increase hepatic fibrosis." (PMID 22719909, 2012). "Based on this approach, we recently identified CO3-610, a specific peptide fragment of type III collagen generated by MMP-9, as a potential liver fibrosis biomarker, and developed an ELISA assay to quantify it in serum." (PMID 21813019, 2011). "The aim of this study was to develop an ELISA detecting a fragment of type VI collagen generated by MMP-2 and MMP-9, and evaluate this assay in two preclinical models of liver fibrosis." (PMID 21935455, 2011). "CSE might also modify elements related to ECM degradation or turnover, because caffeine decreased MMP‐2 and MMP‐9 activity in a rat model of liver fibrosis, and cocoa procyanidins inhibited the expression and activation of MMP‐2 in human vascular SMCs." (PMID 40321100, 2025). "Notably, the combination therapy showed the most substantial reduction in TGF-β and MMP-9 levels, suggesting a complementary protective mechanism against acitretin-induced hepatic fibrosis." (PMID 40866495, 2025). "In addition, daclatasvir has been shown previously to downregulate MMP9 in rat models of hepatic fibrosis, along with other immunoregulatory factors, but did not have an effect on MMP9 mRNA or protein in the RDEB fibroblasts." (PMID 38462666, 2024). "Additionally, increased MDA levels and decreased TAC and GPX levels pointed to lipid peroxidation, while upregulation of MMP2 and MMP9 indicated liver fibrosis progression." (PMID 39185304, 2024). "The expression levels of various proteins, specifically PIK3CB, AKT, pAKT, HDAC3, HDAC6, MMP9, MMP2, VIM, and α-SMA, which are implicated in hepatocyte degeneration as well as the initiation and progression of liver fibrosis, were analyzed using Western blotting." (PMID 39683581, 2024). "Furthermore, the protein–protein interaction (PPI) network analysis based on the STRING database and GOIs provided insights into the functional relationships among key proteins in liver fibrosis, such as Col1a2, Col5a2, MMP9, Col4aa, Col27a1, and Col5a3." (PMID 38874114, 2024). "Additionally, IL-1β promotes liver fibrosis by activating hepatic stellate cells via matrix metallopeptidase 9 (MMP9)." (PMID 36835145, 2023). "Moreover, MMP-9 activity is actively involved in liver fibrosis and bleomycin-induced pulmonary fibrosis." (PMID 38235425, 2023). "Thus, the effects of corylin on the expression of TIMP-1 and MMP-9 in macrophages and Kupffer cells should be further studied to clarify the mechanism by which corylin inhibits liver fibrosis." (PMID 38069259, 2023). "Some researchers have noted an increase in the expression of the MMP-9 proteinand corresponding mRNA in the presence of progressing liver fibrosis, while theetiological factors causing fibrosis are not that important." (PMID 37538808, 2023). "The altered inhibition by TIMP1 of the activity of MMP-9 promotes liver fibrosis." (PMID 38001866, 2023).
liver fibrosis (continued). "MMP9 has a wide proteolytic activity and has an affinity for type IV collagen, the most abundant constituent of basal membrane, and its degradation is key in the progression of lung and liver fibrosis." (PMID 37869492, 2023). "Collectively, these results indicate that administering either P. copri or L. murinus alone, or both together, could alleviate DDC-induced liver fibrosis by downregulating the expression of Collagen 1a1, Mmp9, and α-SMA." (PMID 37446187, 2023). "MMP-9 plays an important role in extracellular matrix remodeling during hepatic fibrosis." (PMID 36012166, 2022). "TIMP-1 and -2 block MMPs such as MMP-2 and MMP-9, which are involved in inhibiting liver fibrosis." (PMID 36232681, 2022). "Feng, Ding revealed that in a mouse model of liver fibrosis, Kupfer cells (KCs) depletion delayed resolution, and adoptive transfer of KCs from WT animals expedited resolution compared to KCs from MMP9/ mice, implying that KC-derived MMP9 is required for fibrosis reversal." (PMID 36435779, 2022). "Down-regulating the expressions of the MMP9 can attenuate CCl4-induced liver fibrosis in rats." (PMID 35330838, 2022). "Since the KO‐BDL mice had a significantly lower Sirius red‐stained area than the WT‐BDL mice, the lower PP in the MMP‐9 KO mice may at least partially have been related to the amelioration of liver fibrosis." (PMID 34647412, 2021). "Therefore, decreased MMP9 activity can contribute to increased liver fibrosis in αSMACreER;Foxf1−/− mice." (PMID 30670377, 2019). "In a model of murine liver fibrosis induced by carbon tetrachloride (CCl4), administration of PRI-724 (the inhibitor of CBP/β-catenin interaction) accelerated the resolution of liver fibrosis accompanied by an increase in MMP-9, MMP-2, and MMP-8 levels in intrahepatic leukocytes." (PMID 30308992, 2018). "MMP-9 is one of the most relevant MMPs that degrades normal liver matrix, and it could promote the development of liver fibrosis." (PMID 29311932, 2017). "Overall, the agents targeting MMP9 for the therapy of liver fibrosis is worthy to be explored." (PMID 27907201, 2016). "Besides, in the liver fibrosis model, infused bone marrow-derived cells migrate to the injured liver through the expression of MMP-9." (PMID 27130910, 2016). "This imbalance toward TIMP-1 may justify the highest levels of stiffness in HCV monoinfected individuals, suggesting that the TIMP-1/MMP-9 ratio mirrors the progression of hepatic fibrosis better than TIMP-1 levels." (PMID 27023536, 2016). "The present study was designated to correlate the levels of MMP-2, MMP-9 and TNF-α with the pathogenesis of chronic liver diseases (CLD) caused by HCV, it also aimed at using them as possible non-invasive serum markers for liver fibrosis." (PMID 26464613, 2015). "In the context of our in vivo and in vitro observations, the reduction of TGFβ1 and MMP-9 in serum and in stimulated monocytes could be related with reduced monocyte liver infiltration and development of liver fibrosis as previously stated." (PMID 25502575, 2014). "Stimulation of liver fibrosis in AnxA1-KO animals was unrelated to regulation of hepatic TGF-β1 or of MMP-9 and MMP-13, suggesting that additional factors may contribute to the profibrogenic evolution of NASH." (PMID 24668763, 2014). "Moreover, antagonization of TIMP-1 by a catalytically inactive mutant MMP-9 or by TIMP-1 neutralizing antibody decreases liver fibrosis." (PMID 23755201, 2013). "The scope of the present study was to develop a novel enzyme-linked immunosorbent assay (ELISA) for the measurement of a MMP-9 and MMP-12-generated biglycan neo-epitope and to test its biological validity in a rat model of RA and in two rat models of liver fibrosis, chosen as models of ECMR." (PMID 23635022, 2013). "Thereby a fragment of type III collagen generated in vitro by MMP-2 and MMP-9 may be a biochemical marker for liver fibrosis." (PMID 23249435, 2012).